SIRT1 (sirtuin 1)
Diseases named in the same sentence as SIRT1 in open-access papers (continued):
Sharing a sentence is not in itself a finding about the gene and the disease.
Insulin resistance (continued). "Studies on hepatic insulin resistance also reported an inhibitory effect of upregulated HOTAIR on SIRT1 expression." (PMID 34685689, 2021). "In cells with insulin resistance, SIRT1 is significantly reduced, resulting in impaired glucose tolerance." (PMID 33546744, 2021). "Sirt1 expression was shown to be reduced in diabetic hearts and resulted in insulin resistance, mitochondrial dysfunction, and impaired antioxidant defenses." (PMID 35096293, 2021). "The caspase-1 associated pathways in lipid metabolism include, along with interleukins, SREBS (and lipid biosynthesis), FABS (and lipid absorption and VLDL secretion), SIRT1 (and adipogenesis and insulin resistance), and others." (PMID 34502478, 2021). "Naltrexone, a TLR4 antagonist, has been found to diminish hyperinsulinemia-mediated insulin resistance via activation of SIRT1." (PMID 34071497, 2021). "The evidence suggests that the activation of AMPK signaling suppresses the expression of the nuclear factor-kappa B (NF-κB) by increasing the expression of SIRT1, thereby contributing to the protection against obesity, inflammation, and insulin resistance." (PMID 34656137, 2021). "In contrast, most of the class III HDACs, such as SIRT1, 2, 3, and 6 were claimed to impede insulin resistance and impart beneficial effects by suppressing inflammation, oxidative stress, and mitochondrial dysfunctions in the DM-affected tissues." (PMID 34071497, 2021). "Deacetylation of Lys268 and Lys293 on PPARγ induced by SIRT1 recruits the BAT program coactivator Prdm16, leading to the selective induction of BAT genes and repression of WAT genes associated with insulin resistance." (PMID 34421358, 2021). "We looked at the beneficial effects of SRT1720, a Sirt1 activator, Oroxylin-A, a Sirt3 activator, and their combination in insulin resistance/pre-diabetic rat heart." (PMID 33668369, 2021). "Upregulation of SIRT1 in muscle cells protects against the effects of glucose-induced insulin resistance, through the reduction of mitochondrial dysfunction and oxidative stress, by increasing levels of SIRT3." (PMID 33806509, 2021). "Vitamin K2 supplements in mice also increase mitochondrial functioning via SIRT1 pathways and alleviates insulin resistance in the skeletal muscle tissue." (PMID 33806509, 2021). "In the present study, we aimed to evaluate the effect of Sirt1, Sirt3 and combined activation in high fructose diet-induced insulin resistance rat heart and assessed the cardiac function focusing on mitochondrial health and function." (PMID 33668369, 2021). "When Sirt1 KO mice were fed a high-fat diet, they showed hepatic steatosis, insulin resistance, and other severe metabolic syndromes, suggesting that Sirt1 plays a vital role in regulating glucose and liver lipid homeostasis." (PMID 33562281, 2021). "Adipocyte specific ablation of Sirt1 induces increased adiposity and manifestation of metabolic dysfunction including insulin resistance." (PMID 32796716, 2020). "Although the beneficial role of Sirt1 has been evaluated across the context of multiple diseases such as inflammation and insulin resistance, the process through which it prevents apoptosis requires further investigation." (PMID 33363155, 2020). "Sirt1 agonists are known to have protective effects on the metabolism of some diabetic animals, including glucose tolerance, fasting glucose level, and insulin resistance." (PMID 33519483, 2020). "Our results provide a novel insight into the molecular mechanisms involved in BBR’s action on insulin resistance and inflammation, and identify adipose tissue SIRT1 as a key regulator of the insulin sensitizing and anti-inflammatory effects of BBR." (PMID 33390968, 2020). "The decreased expression and activity of Sirt1 is involved in the pathogenesis of insulin resistance, DT2 and liver steatosis." (PMID 32796716, 2020).
Insulin resistance (continued). "In response to high-fat diet, accelerated adiposity, exacerbated insulin resistance, and severe brown adipose tissue degeneration phenotype were displayed in SIRT1+/−mice." (PMID 32781630, 2020). "MTPα deacetylation mediated by 9-PAHSA or resveratrol, a SIRT1 agonist, decreased insulin resistance." (PMID 33009367, 2020). "It was very recently shown that Que (70 mg/kg) can reduce insulin resistance and improve glucose metabolism by reducing sensitivity to T2D/insulin resistance in ob/ob mice via SIRT1 activation." (PMID 32848804, 2020). "Taken together, these data highlight the decreased activity of Sirt1 as a key component of the molecular mechanisms that produce the outcomes of metabolic syndrome and insulin resistance." (PMID 32796716, 2020). "Metformin can overcome hyperglycemia-induced insulin resistance in podocytes by promoting the expression and function of SIRT1 and AMPK." (PMID 32364526, 2020). "SIRT1 is also an important regulator of insulin sensitivity, as systemic knockout of Sirt1 leads to insulin resistance." (PMID 33321755, 2020). "Recent findings revealed that there is a significant reverse relation between gene expression of SIRT1 protein in peripheral blood mononuclear cells and insulin resistance and it decreases particularly in glucose intolerance subjects." (PMID 31901246, 2020). "A previous report showed that decreased Sirt1 expression levels in circulating monocytes are correlated with insulin resistance in humans." (PMID 33053742, 2020). "In a study, the expression of SIRT1 is reduced in myotubes and skeletal muscle isolated from T2D patients, who suggested the down-regulation of SIRT1 related to insulin resistance evoked by TNF-α in skeletal muscle." (PMID 32815547, 2020). "In summary, Sirt1 acts as a sensor of the nutritional status on molecular mechanisms related with metabolic syndrome and insulin resistance, in pancreatic beta cells, adipose tissue and skeletal muscle." (PMID 32796716, 2020). "The activation of AMPK, SIRT1, FOXO3a and NF-κB signaling by TNF-α has been reported to cause inflammation and insulin resistance in several cell lines." (PMID 31100089, 2019). "The activation of SIRT1 can improve insulin resistance, increase fatty acid oxidation, and mitochondrial biogenesis in the skeletal muscle." (PMID 30658634, 2019). "SIRT1 can be involved in the regulation of metabolism and insulin resistance through the modulation of mitochondrial function." (PMID 30972029, 2019). "In contrast, increased SIRT1 activity had a protective effect against insulin resistance in the liver in mice exposed to a HFD." (PMID 31214115, 2019). "In humans, reduction of SIRT1 expression levels in circulating monocytes is correlated with glucose intolerance, insulin resistance and metabolic syndrome in humans." (PMID 30972029, 2019). "In humans, several small trials have shown that SIRT1 activators exert beneficial effects on glucose metabolism and insulin resistance, which resemble the effect of CR." (PMID 30972029, 2019). "MiR-138-5p contributed to the TNF-α-induced insulin resistance through inducing autophagy in HepG2 cells by regulating SIRT1." (PMID 30736838, 2019). "SIRT1 overexpression protects C2C12 myotubes against fatty acid-induced insulin resistance through transcriptional repression of PTP1B." (PMID 30574122, 2018). "Although the precise mechanism(s) by which CR can lower BP and improve autonomic nervous system and endothelial function are as yet unclear, potential candidates include reducing insulin resistance, improving nitric oxide production and upregulating SIRT1." (PMID 29518898, 2018). "Studies have shown that lower SIRT1 activity is involved in the pathogenesis of DM and insulin resistance." (PMID 29343256, 2018). "AMPK acts as a sensor, and when activated, stimulates mitochondrial biogenesis, energy production, lipid oxidation, and glucose influx, alleviating insulin resistance via activation of sirtuin 1 and PGC1α." (PMID 30428888, 2018).
Insulin resistance (continued). "Potential mechanisms linking CR to improvement in BP and endothelial function comprise reduction in insulin resistance, improved nitric oxide production and induction of SIRT1." (PMID 29518898, 2018). "Anthropometrics, plasma lipid and insulin resistance profiles and nutrient intakes were analyzed with regard to 3 genotypes of SIRT1 rs7895833 (GG, GA, and AA)." (PMID 29291737, 2018). "Our previous work has committed that EA provides a beneficial effect on insulin resistance in obese and diabetic db/db mice via stimulation of Sirtuin 1 (Sirt1)." (PMID 30425749, 2018). "Conversely, Zang and colleagues showed that adenovirus-mediated hepatic overexpression of SIRT1 attenuates insulin resistance, restores glucose homeostasis, and ameliorates hepatic steatosis." (PMID 29207650, 2017). "The reduced SIRT-1 functionality could be the consequence of OS and is likely linked to hepatic fibrosis, microsteatosis and impaired hepatic insulin signaling and glucose transporters, leading to insulin resistance and glucose intolerance observed at adulthood." (PMID 29018245, 2017). "In this study, we found altered mediators implicated in insulin resistance and cognition, including adiponectin, PPARγ, ERK1/2, p66Shc, SIRT1 and BDNF." (PMID 29340106, 2017). "It should be noted that we did not further confirm the role of miR-377 in the regulation of SIRT1 expression and SIRT1-mediated inflammation and insulin-resistance by using miR-377 mimics and inhibitor in an animal model." (PMID 29050301, 2017). "Our data showed that SIRT1 overexpression in hepatocytes attenuated NEFA-induced insulin resistance, glucose metabolic derangements and lipid accumulation." (PMID 29207650, 2017). "The diabetic patients manifest insulin resistance when the expression and activity of SIRT1 were inhibited in hepatocyte, showing that SIRT1 contributes to hepatic insulin sensitivity." (PMID 27659520, 2017). "Taken together, these results provide additional support about the role of TQ in improving insulin resistance, as well as show that this action is likely mediated by SIRT-1 activation." (PMID 28950020, 2017). "MiR-543 is known to target SIRT1 in gastric cancer, and miR-543-mediated targeting of SIRT1 is known to alleviate insulin resistance." (PMID 28589857, 2017). "For example, SIRT1 protected from experimental autoimmune encephalomyelitis, arthritis, lung inflammation, hepatic steatosis, and insulin resistance, but promoted lupus, arthritis, allergic airway disease, and allograft rejection." (PMID 28894448, 2017). "Taken together, these results suggested that SIRT1 inhibition is required for miR-377-mediated inflammation and insulin-resistance." (PMID 29050301, 2017). "Sirt1 adipocyte-specific knockout mice present low-grade chronic inflammation along with glucose intolerance and insulin resistance." (PMID 28030827, 2017). "Recent study shows that overexpression of Sirt1 attenuates hepatic steatosis and ER stress condition, ameliorates insulin resistance, and restores glucose homeostasis." (PMID 28030827, 2017). "MiR-377 upregulation results in post-transcriptional SIRT1 silencing, which contributes to adipose tissue inflammation and insulin-resistance." (PMID 29050301, 2017). "A previous report has shown that Sirt1 expression is decreased in monocytes from patients with insulin resistance." (PMID 27744418, 2016). "In experimental animals, activation of SIRT1 was reported to offer protection against obesity and insulin resistance by positively regulating the secretion of insulin." (PMID 28050570, 2016). "The relationship among Sirt1, inflammation, vascular aging and atherosclerosis has been demonstrated and contributes to metabolic disorders such as insulin resistance." (PMID 27744418, 2016). "Accumulating evidence suggests that SIRT1 and SIRT1 activators can prevent and reverse insulin resistance and diabetic complications, proven to be a promising therapeutic target in type 2 diabetes (T2D)." (PMID 27916001, 2016).
Insulin resistance (continued). "Adipose tissue-specific SIRT1 deletion in mice led to increased adiposity and metabolic dysregulation, including insulin resistance." (PMID 26655722, 2016). "More recently, we reported that rodents carrying a liver-SIRT1 knockout exhibited hyperglycemia and had an increase in gluconeogenesis, which lead to insulin resistance." (PMID 26890260, 2016). "The results from the same study were further supported by a development of hepatic insulin resistance in rats fed normal chow following a duodenum-specific knockdown of SIRT1 expression for 14 days." (PMID 28050570, 2016). "SIRT1-mediated decrease of insulin resistance has been proposed, mainly based on resveratrol treatment, although the participation of SIRT1 as a nuclear deacetylase is far from being clearly demonstrated in these studies." (PMID 27366200, 2016). "Although SIRT1 can increase cell survival and preserve insulin signaling by blocking apoptotic pathways, SIRT1 also can foster autophagy and limit mTOR activation to preserve mitochondria, promote stem cell proliferation, and prevent insulin resistance." (PMID 26064426, 2015). "In mature and differentiated cells, SIRT1 can prevent insulin resistance through a number of mechanisms that involve fat mobilization, mTOR signaling, and control of cellular inflammation." (PMID 26064426, 2015). "In this context, another study showed that restriction of AGEs in a cohort of patients with T2DM reduced insulin resistance and increased expression of SIRT1 and AGER1." (PMID 25786107, 2015). "Additional reports demonstrate that the deacetylase activity of SIRT1 is involved in proper glucose metabolism, indicating a potential implication for the importance of SIRT1 and related antioxidants for the treatment of insulin resistance." (PMID 26435910, 2015). "Conversely, whole body SIRT1 overexpression confers protection against HFD-induced insulin resistance, mostly by maintaining the ability of insulin to block hepatic glucose production." (PMID 24567900, 2014). "Sirt1 is decreased in a rat model of NAFLD and Sirt1 hepatic deficiency leads to oxidative damage and insulin resistance." (PMID 24672550, 2014). "An in vitro study showed that Res, a Sirt1 activator, enhanced insulin sensitivity in a Sirt1-dependent manner and attenuated high-fat-diet-induced insulin resistance." (PMID 25140191, 2014). "PARP-1 deficient mice also show a number of phenotypes resembling SIRT1 transgenesis and pharmacological activation, most notably a remarkable protection against HFD-induced insulin resistance." (PMID 24567900, 2014). "Proteins involved in enhancing mitochondrial function and limiting ROS accumulation, such as PGC-1α, Sirt1, and Sirt3, are of interest as specific therapeutic targets to improve insulin resistance observed in NAFLD progression." (PMID 24672550, 2014). "SIRT1 activation promotes mitochondrial energy expenditure, prevented the onset of obesity, ameliorated dyslipidemia and reduced insulin resistance in rodents and humans." (PMID 24759758, 2014). "Our result is in line with previous study which reported overexpression of SIRT1 protected insulin resistance and improved metabolic parameters." (PMID 24009212, 2013). "New data shows that high-fat diet feeding-induced caspase-1 can deactivate Sirt1 and leads to insulin-resistance." (PMID 23483669, 2013). "SIRT1 is also an important regulator of macrophage inflammatory responses in the context of insulin resistance." (PMID 23734259, 2013). "It is well established that the effect of SIRT1 on insulin resistance is mediated by the repression of PTP1B transcription at the chromatin level." (PMID 23442260, 2013). "The improvement of insulin sensitivity by SIRT1 has implications in the treatment of insulin resistance and type 2 diabetes." (PMID 23442260, 2013). "In summary, AICAR negatively regulates HF diet-induced inflammation, which requires myeloid SIRT1, thereby contributing to the protection against insulin resistance." (PMID 23183898, 2012).
Insulin resistance (continued). "The Sirt1 activator resveratrol extends lifespan and protects against diseases such as insulin resistance." (PMID 23185430, 2012). "SIRT1 can attenuate hepatic steatosis, ameliorate insulin resistance, and restore glucose homeostasis primarily through the inhibition of mTORC1." (PMID 23203037, 2012). "The beneficial effects of AICAR in antagonizing inflammation and insulin resistance require myeloid SIRT1." (PMID 23183898, 2012). "The AMPK activators metformin and A-769662, as well as resveratrol, a polyphenolic SIRT1 activator, ameliorate insulin resistance in animals given a high-fat diet." (PMID 23137106, 2012). "Taken collectively, these findings implicate SIRT1 activation as a potential therapeutic target in overcoming insulin resistance." (PMID 20981161, 2011). "The study introduces an effective and safe activator (electroacupuncture) for SIRT1, offering a basis for applying acupuncture in clinical practice in the treatment of diseases related to insulin resistance." (PMID 20981161, 2011). "Accordingly, Sirt1 activators improve insulin resistance in ob/ob and diet-induced obese mice, and increase insulin sensitivity in obese, insulin-resistant Zucker rats." (PMID 21426570, 2011). "A recent study showed that EA offers a beneficial effect on insulin resistance in obese and diabetic db/db mice, at least partly, via stimulation of SIRT1/PGC-1α, thus resulting in improved insulin signaling." (PMID 21754922, 2011). "Remarkably, SIRT1 activators enhance insulin sensitivity in vitro and ameliorate insulin resistance in vivo in a SIRT1-dependent manner." (PMID 20981161, 2011). "Further, SIRT1 can protect against insulin resistance by deacetylating the substrate PGC-1α and increasing PGC-1α activity." (PMID 20981161, 2011). "While increased 1-MNA enhances NAD+ salvage pathways to mitigate mitochondrial oxidative stress, it may paradoxically compromise sirtuin-1 activity, exacerbating insulin resistance and de novo lipogenesis." (PMID 41280393, 2025). "SIRT1 was found to negatively correlate with NFκB, insulin resistance, and oxidative stress." (PMID 40166461, 2025). "Inconsonance a recent study demonstrates that sirtuin 1 can predict worsened insulin resistance." (PMID 40481568, 2025). "Furthermore, correlation analysis revealed that SIRT1 was negatively correlated with NFκB, insulin resistance, and oxidative stress, while positive correlations were observed between SIRT1, p-AKT, and Nrf2 activity." (PMID 40166461, 2025). "Notably, Sirt1 overexpression, particularly in skeletal muscle, has been demonstrated to counteract the development of insulin resistance induced by a high-fat diet in mice." (PMID 38203812, 2024). "Therefore, it has been suggested that the protective effect of AMPK on insulin resistance in PCOS rats is mediated by the AMPKα-SIRT1 signaling pathway." (PMID 39268230, 2024). "The study speculated that the possible mechanism was that the decrease of SIRT1 expression led to the aggravation of insulin resistance and inflammatory reaction, which led to the occurrence of type 2 diabetes comorbid depression." (PMID 39612426, 2024). "BBR inhibits sarcopenia-induced insulin resistance through SIRT1-mediated mitochondrial autophagy." (PMID 39421985, 2024). "Similarly, mice carrying an adipocyte-specific deletion of SIRT1 developed insulin resistance and AT inflammation." (PMID 38255934, 2024). "In addition, it has been found that AMPK/SIRT1 has significant therapeutic effects on insulin resistance in the ovaries, although further study is required to elucidate its specific mechanism of action." (PMID 36975503, 2023). "Moreover, a study focused on insulin resistance showed that overexpression of miR‐543 lowered SIRT1 mRNA and protein levels in different gastric cell types, indicating a negative correlation between miR‐543 and SIRT1 expression." (PMID 36352829, 2023).